CD1B (CD1b molecule)
Diseases named in the same sentence as CD1B in open-access papers (continued):
Sharing a sentence is not in itself a finding about the gene and the disease.
breast carcinoma (1 paper, 2020). "Similar result was found in our study, that was, low expression of CD1B was likely to cause metastatic recurrence of breast cancer." (PMID 32867782, 2020). "High expression of THY1 was more likely to cause metastasis of breast cancer, while low expression of CD1B and DOCK2 was likely to cause metastasis of breast cancer." (PMID 32867782, 2020). "CD1B (CD1b molecule), THY1 and DOCK2 (dedicator of cytokinesis 2) were found to be implicated in the metastatic recurrence of breast cancer." (PMID 32867782, 2020). "THY1 and NEU2 may be potential therapeutic targets for breast cancer with brain metastases, and THY1, CD1B and DOCK2 may serve as potential prognostic markers for improvement of brain metastases survival." (PMID 32867782, 2020).
colitis (1 paper, 2022). Inflammation of the colon. "Additionally, Adamdec1 knockout mice showed increased sensitivity to the DSS colitis, associated with neutrophilic (CD1B+ GR1+ F480−) infiltrate." (PMID 35563399, 2022).
colorectal cancer (1 paper, 2022). A primary or metastatic malignant neoplasm that affects the colon or rectum. "The high expression of CD1B exhibited a significant correlation with longer OS in colorectal cancer." (PMID 36727052, 2022).
Crohn disease (1 paper, 2024). A gastrointestinal disorder characterized by chronic inflammation involving all layers of the intestinal wall, noncaseating granulomas affecting the intestinal wall and regional lymph nodes, and transmural fibrosis. "The first identification of CD1b/c “patch” implies the presence of any other motifs for known biased TCR Vβ genes, such as TRBV7-9+ T cells restricted by human CD1c or CD1d, which are associated with Crohn’s disease." (PMID 39718834, 2024).
HCMV infection (1 paper, 2018). "Group 1 CD1 molecules are downregulated from the cell surface during the early phase of HCMV infection with CD1b being especially sensitive to this effect." (PMID 29616036, 2018).
leukemia (1 paper, 2013). A malignant (clonal) hematologic disorder, involving hematopoietic stem cells and characterized by the presence of primitive or atypical myeloid or lymphoid cells in the bone marrow and the blood. "For example, the combination of GM-CSF, IL-4, and TNFα induced the expression of MHC II, CD40, CD86, CD1a, CD1b, and CD1c by neutrophil-committed precursors isolated from leukemia patients receiving G-CSF treatments." (PMID 24278484, 2013).
melanoma (1 paper, 2023). A malignant, usually aggressive tumor composed of atypical, neoplastic melanocytes. "Evidence of the expression profile of β2M, CD1d, and CD1b in melanoma tissues can be found in the Human Protein Atlas collection." (PMID 37077920, 2023). "Co-expression and correlation profile of B2M with CD1D, CD1B, and FCGRT dissociates in melanoma patients following B2M expression loss." (PMID 37077920, 2023). "As opposed to the cell membrane region, β2M, CD1d, and CD1b were mostly expressed in the cytosol of malignant melanoma tissues." (PMID 37077920, 2023). "To evaluate whether the expression of CD1D, CD1B, and FCGRT is affected in a β2M-dependent manner in malignant melanoma, we first obtained the expression levels of all β2M-STRING-predicted interacting genes (n = 20) from the GDC-TCGA-SKCM study." (PMID 37077920, 2023). "We provide further evidence that epigenetic changes in the TME of melanoma tumors have a direct impact on B2M and an indirect impact on CD1D gene expression (through SPI1) but not on CD1B and FCGRT expression in melanoma patients from the TCGA dataset." (PMID 37077920, 2023).
metastatic melanoma (1 paper, 2023). A melanoma that has spread from its primary site to another anatomic site. "We evaluated whether the differential expression of B2M and its correlated genes (CD1D, CD1B, and FCGRT) is associated with poor responses to anti-PD1 in metastatic melanoma." (PMID 37077920, 2023).
pulmonary TB (1 paper, 2024). "In this study, we utilized the guinea pig model of pulmonary TB and reagents specific to CD1b orthologs to kinetically measure CD1b-restricted immunity at multiple stages of TB disease within the lung and spleen." (PMID 39494875, 2024).
Salmonella Infections (1 paper, 2013). Infections with bacteria of the genus SALMONELLA. "Our results suggest that this is what occurred in the present in vitro study as IL-23 transcripts in CD1b+ L-DCs were detected after Salmonella infection, but possibly in insufficient quantities to promote IL-17 production by CD4+ T cells." (PMID 24223964, 2013). "Unlike CD1b+ L-DCs, CD1b- L-DCs were constitutively predisposed to promote a Th17 and Th2 response which were down-regulated after Salmonella infection but not after stimulation with helminth secretions." (PMID 24223964, 2013). "Salmonella infection reduced the constitutive expression of TNF-α and IL-4 mRNA in CD1b- L-DCs, whereas this expression was not affected by helminth secretions." (PMID 24223964, 2013).
T cell lymphoma (1 paper, 2025). "Furthermore, these T cells were able to lyse CD1b-transfected, but not wild-type, murine RMA-S T cell lymphoma cells, confirming CD1b-restricted recognition and cytotoxicity." (PMID 40709176, 2025).
triple-negative breast carcinoma (1 paper, 2020). An invasive breast carcinoma which is negative for expression of estrogen receptor (ER), progesterone receptor (PR), and human epidermal growth factor receptor 2 (HER2). "Based on the analysis of the bc-GenExMiner v4.4 database, CD1B, THY1 and DOCK2 were found to affect the metastatic recurrence of triple-negative breast cancer." (PMID 32867782, 2020).
type 2 diabetes (1 paper, 2017). "We tested this hypothesis by analyzing a public data set for CD1 molecule expression among metabolically healthy adults, pre-diabetic adults, and adults with type 2 diabetes and we found that CD1a and CD1b are significantly downregulated in the diseased state." (PMID 28463985, 2017).
infection (21 papers, 2012 to 2025). The state of being infected such as from the introduction of a foreign agent such as serum, vaccine, antigenic substance or organism. "Therefore, the ability of M. leprae MDP to induce both IL-32 and CD1b+ DC is linked to host defense at the site of infection." (PMID 27297389, 2016). "Another molecule downregulated by infection was CD1-b, which recognizes various lipids—including microbial lipid antigens—and is present on T and NK cells." (PMID 41398915, 2025). "(2011) further demonstrated that mycolic acid-specific CD1b-restricted T cells were enriched in TB patients, including at the site of infection (bronchoalveolar lavage fluid), and persisted long after treatment, indicating durable memory responses." (PMID 40709176, 2025). "Owing to the lack of an anti-guinea pig CD3 antibody for flow cytometry, we sought to further discriminate the CD45+ leukocyte populations expressing CD1b over the course of infection based on scatter parameters." (PMID 39494875, 2024). "Collectively, all CD1b orthologs increased expression over the course of Mtb infection, with peak expression for CD1b1-3 occurring at day 30 of infection." (PMID 39494875, 2024). "Leukocytes derived from lung parenchyma had reduced (P < 0.05) surface CD1b expression at day 14 of infection (mean 6.2% ± 3.4%) compared to naïve uninfected controls (mean 11.3% ± 1.9%)." (PMID 39494875, 2024). "To examine the kinetics in vivo, we evaluated the influence of Mtb infection on CD1b expression over the course of TB disease in two independent in vivo infection studies in the spleen and lung of Mtb-infected guinea pigs among viable CD45+ leukocytes." (PMID 39494875, 2024). "In vitro, human antigen-presenting cells can induce CD1b in response to mycobacterial exposure, suggesting a natural response whereby CD1b can locally function near infection." (PMID 39494875, 2024). "The frequency of CD1b expressing leukocytes remained similarly elevated at day 60 of infection with a mean of 10.2% ± 3.3% CD1b+ compared to day 14 of infection (P = 0.05) and was greater than naïve time-matched controls (P < 0.01)." (PMID 39494875, 2024). "Overall, this work demonstrates that CD1-restricted immunity actively responds to Mtb, as manifested by CD1b-mediated cytolytic responses to mycobacterial lipid antigens, indicating a pathogen-specific in vivo response to infection." (PMID 39494875, 2024). "In the spleen, CD1b expression was increased at all three infection endpoints compared to time-matched naïve controls (P < 0.05 – P < 0.01)." (PMID 39494875, 2024). "By contrast, lung-derived small-cell leukocytes had significant upregulation over the course of infection, increasing from 7.6% ± 3.6% CD1b+ at day 14 of infection to 16.7% ± 5.4% CD1b+ at day 60 of infection in the lung (P < 0.001)." (PMID 39494875, 2024). "CD1B is recognized as a marker by γδ T cells and plays an important role as an effector of tissue injury, infection, and cancer development; it also regulates the differentiation and maturation of dendritic cells." (PMID 36221049, 2022). "While CD1a is constitutively expressed on epidermal Langerhans cells, CD1b is normally rare in the skin, but has been shown to be upregulated in the dermis after infection with Borrelia burgdorferi." (PMID 34914694, 2021). "Based on our gene expression analysis of rabbit lung, while there was an increase in CD1B expression at the onset of M. tuberculosis infection, the levels dropped as the infection progressed." (PMID 31167948, 2019). "Although most studies of CD1b focus on infection, recent studies have identified a role for CD1b in T cell autoreactivity, including CD1 tetramer–guided studies in humans and human TCR transgenic mice, identifying self-phospholipids as antigenic targets." (PMID 29054999, 2017). "The infection of CD1b+ L-DCs with Salmonella for 6h induced a significant increase in IL-1ß, IL-6, IL-12p40 and IL-10 mRNA, whereas only IL-6 mRNA increased after Hc-ES stimulation." (PMID 24223964, 2013).
infection (continued). "To characterize the flexible response of mature conventional CD1b+ L-DCs to pathogens, we analysed the cytokine mRNA produced by CD1b+ L-DCs after infection with Salmonella or stimulation with Hc-ES." (PMID 24223964, 2013). "The ability of CD1b+ L-DCs to present bacterial antigens to specific T cells, induced in vivo by SC infection of sheep by Salmonella, was also investigated." (PMID 22279590, 2012). "The identification of CD1b induction by day 14 of infection may suggest a role for this induction in the early pulmonary response to Mtb infection." (PMID 39494875, 2024). "Moreover, we demonstrate local CD1-restricted cytotoxicity targeting two group 1 CD1b proteins, CD1b1 and CD1b3, which is evident in the pulmonary response at day 14 of infection and established disease at day 60 of infection in the spleen." (PMID 39494875, 2024). "At day 60 of infection, corresponding to the point of greatest CD1b expression, specific cytotoxicity was observed in spleen tissue against CD1b1 loaded with either glucose monomycolate (P < 0.05) or mycolic acid (P < 0.001) and against CD1b3 loaded with glucose monomycolate (P < 0.01)." (PMID 39494875, 2024). "Correlating with flow cytometric analyses, CD1b was kinetically regulated during the course of Mtb infection, with the highest number of CD1b expressing cells appreciated at 30 days post-infection, with a mean of 21,369 ± 9,829 CD1b+ cells per animal among lung granulomas." (PMID 39494875, 2024). "The frequency of CD1b-expressing cells in lungs of infected animals was increased at day 30 of infection compared to day 14 (P < 0.001), where there were a mean of 11.8% ± 2.8% CD1b+ cells in the infected lung, compared to 9.4% ± 5.3% CD1b+ cells among naïve, uninfected guinea pigs." (PMID 39494875, 2024). "infection of human monocyte-derived dendritic cells resulted in reduced expression of CD1b." (PMID 32131896, 2020). "To investigate the role of Notch ligands expressed by DCs in response to pathogens, and in possible polarized cytokine T cell response, we analysed the expression of the Notch ligands Jagged-1 and Delta-4 by CD1b+ L-DCs before and after infection with Salmonella or stimulation with Hc-ES." (PMID 24223964, 2013). "Thus, CD1b-restricted responses may be more localized to the site of infection as compared to the systemic nature of MHC-restricted responses." (PMID 39494875, 2024). "In summary, here we report the first structure of an αβ TCR bound to CD1b–antigen complex, and simultaneously provide a molecular basis into how the immune system uses conserved recognition features to target a mycobacterial lipid antigen formed during infection of the host." (PMID 27807341, 2016). "They found that infection with live BCG inhibited the GM-CSF-induced upregulation of group 1 CD1 molecules, particularly CD1b." (PMID 40709176, 2025). "The aim of the present study was to evaluate the expression of different markers of DC (CD1b, CD83 and MHC-II) and of FDC (CNA.42, S100 and CD83) in the HLNs and liver of sheep during the early stages of infection with F. hepatica." (PMID 32131896, 2020). "Regardless of the infection endpoint, CD1b ortholog-expressing target cell, or Mtb lipid antigen, no cytotoxic effect was demonstrated among PBMCs isolated from infected guinea pigs compared to PBMCs from naïve guinea pigs." (PMID 39494875, 2024). "Only IL-12p40 mRNA was observed to increase significantly 18h after the infection of CD1b+ L-DCs with Salmonella (data not shown)." (PMID 24223964, 2013). "The induction of the highest specific proliferative response of CD4+ T cells to CD1b+ L-DCs primed with Salmonella was observed 21 days after infection, and no proliferative response was observed for CD4− T cells." (PMID 22279590, 2012).
infection (continued). "CD4+ and CD4− T cells were isolated from the blood of three sheep at different times between one and nine weeks after infection to assess their capacity to be activated by CD1b+ L-DCs primed in vitro with Salmonella (data not shown)." (PMID 22279590, 2012). "If activation of CD1b-lipid-specific T cells in the Peruvian cohort were a result of high exposure, but without infection, the healthy blood bank donors in the USA should have lower numbers of CD1b-lipid tetramer+CD45RO+ than “uninfected” but highly exposed subjects in Peru." (PMID 32117314, 2020). "Thus, CD1b-restricted cells do not behave like MHC-restricted cells by increasing in frequency in the blood after infection by Mtb." (PMID 32117314, 2020). "Moreover, one of our in vivo studies showed that CD1b+ L-DCs did not play a major role in Salmonella transport to LN after SC infection of the upper respiratory tract with a live vaccine, despite an increased flow of these cells in the lymph." (PMID 22279590, 2012). "In summary, infection of microglia with MP-12 and ZH501 yielded different outcomes, with downregulation of CD45 and CD1b and no induction of CD86 and CD80 expression in response to ZH501 infection." (PMID 38392897, 2024). "Our data show that infection of MDMs, MDDCs, dMonWC1+, or dMonWC1neg with Map did not significantly alter surface expression of CD163, CD1b, CD205, CD14, CD172a, CD11b, or CD11c at 48 h post infection." (PMID 28588573, 2017).
tumor (18 papers, 2012 to 2025). "In follow-up experiments, mice were inoculated with either wild-type or CD1b-transfected RMA-S tumour cells, alongside CD1b-autoreactive T cells." (PMID 40709176, 2025). "For example, the molecule CD1b (CD1B) is a novel prognostic biomarker in LUAD and related to its tumor mutation burden (TMB) as well as antitumor immunity." (PMID 38764064, 2024). "Our results suggest that in both READ and COAD, the expression level of CD1B is significantly positive correlation with the tumor-infiltrating levels of neutrophils and Dendritic Cells." (PMID 34364366, 2021). "Staining for CADM3, IGLON5, and TGFB1 was low in tumor tissue; staining for LEP and ABI3BP was medium in tumor tissue; staining for CD1B was high in tumor tissue." (PMID 34497681, 2021). "Numerous studies showed that CD1B-restricted T cells responded more effectively to lipid from tumor cells than normal cells and leaded to regulation of tumor growth (Chancellor, Gadola & Mansour, 2018)." (PMID 33996273, 2021). "In this signature, up-regulated DKK1 and GRP together with down-regulated FAS and CD1B had significant correlation with tumor stage, metastasis and lymphatic invasion." (PMID 33996273, 2021). "CD1b has been shown to bind to tumor-derived phospholipids in T-cell lymphoma." (PMID 40746558, 2025). "Next, we evaluated whether B2M, CD1D, and CD1B differential expression are impacted at the tumor cells or DCs levels in the TME." (PMID 37077920, 2023). "The frequencies of positively stained areas of the cell membrane and cytosol within the tumor tissue are as follows: β2M 8.2% (cell membrane) and 39.84% (cytosol); CD1d 6.72% (cell membrane) and 53.83% (cytosol); and CD1b 12.39% (cell membrane) and 55.18% (cytosol)." (PMID 37077920, 2023). "The eight-gene-signature prognostic model (ANGPTL5, CD1B, CD1E, CNTFR, CTSG, EDN3, IL12B, and IL2)-based high- and low-risk groups were significantly related to overall survival (OS), tumor microenvironment (TME) immune cells, and clinical characteristics in LUAD." (PMID 34745015, 2021). "Previous reports have indicated that CD1B-restricted self-lipid-reactive T-cells responded more potently to lipid from tumor cells than to an equivalent amount of lipids from normal cells, and the adoptive transfer of these T-cells into mice resulted in tumor control." (PMID 32508884, 2020). "However, it is a common feature that the number of myeloid derived suppressor cells (MDSC), which are defined as CD1b/Gr-1 double positive cells in mice, is increased in cancer patients and tumor bearing mice." (PMID 22359662, 2012). "Tumour growth was significantly reduced in mice that received CD1b-transfected RMA-S cells and CD1b-autoreactive T cells, suggesting that these T cells can mediate anti-tumour immunity in a CD1b-dependent manner." (PMID 40709176, 2025). "Using previously validated immune gene signatures from bulk RNA datasets to estimate immune cell abundances, we found that B2M and CD1D but not CD1B were significantly enriched on both tumor and DCs cells from patients responding to ICT." (PMID 37077920, 2023). "The CD1A, CD1B, GRP, SERPINE1, and F2RL2 genes were highly expressed in tumor tissue." (PMID 36221049, 2022). "However, the role of FGD3, TMEM176A, CD1B and MATK in anti‐tumor immunity remains unclear." (PMID 36814908, 2023). "In contrast, no reduction in tumour size was observed in mice inoculated with wild-type RMA-S cells, confirming that the protective effect was specifically mediated by CD1b recognition." (PMID 40709176, 2025).
cancer (7 papers, 2012 to 2025). A tumor composed of atypical neoplastic, often pleomorphic cells that invade other tissues. "Among the differentially expressed IRGs, we identified 5 IRGs (CD1B, XCL1, PLCG2, NGF, and OXTR) for inclusion in the risk score, and previous studies have indicated that these genes were related to immune processes and cancer progression." (PMID 32508884, 2020). "We also found five genes discovered by the consensus DEA and PCA and annotated as candidate cancer genes in NCG: AJAP1, CD1B, CDH2, PABPC4L, and PCDH10." (PMID 40788820, 2025). "However, IL-2 secretion was significantly higher when CD1b was loaded with lipids extracted from the T lymphoblast cell line MOLT-4, suggesting that cancer cell-derived lipids are more immunogenic." (PMID 40709176, 2025).
Bacterial Infections (2 papers, 2015 to 2021). "The relative MoDC vs. Mo/MP signature encompasses additional genes that participate in “migration of cells” (p = 10−2.3, with S1PR3, CCL17, and SLC2A1), “bacterial infection” (p = 10−3.2, with CD1B, CD209, and FCGR2B), and “synthesis of nitric oxide” (10−2.5, with PLAU, IL1R2, and NOS2)." (PMID 26150816, 2015).